ARRB1 (arrestin beta 1)
Diseases named in the same sentence as ARRB1 in open-access papers (continued):
Sharing a sentence is not in itself a finding about the gene and the disease.
cancer (continued). "The IHC results clearly indicate that the ARRB1 expression gets downregulated with the advancing cancer stage." (PMID 28559546, 2017). "This ARRB1-mediated “pseudohypoxia” is considered to confer a growth advantage of cancer cells and their adaptation to the rough environment observed in solid tumors." (PMID 28468237, 2017). "Although only the expression of SCF correlated with smoking other nicotine regulated ARRB1 dependent genes from our microarray data also seem to have important role in various cancers." (PMID 25401222, 2014). "Thus, AEP promoted oncogenic splicing of widespread pre-mRNAs via tDDX3X-C, and the PRDM2-Δexon 2 and ARRB1-Δexon 13 isoforms induced by AEP/tDDX3x promote cancer cell proliferation." (PMID 37988165, 2023). "Our results suggest that ARRB1 may serve as a promising prognostic biomarker in cancers such as KIRC and LUAD." (PMID 36213111, 2022). "In conclusion, our results contribute to elucidating the immunotherapeutic role of ARRB1 in cancer and may serve as a reference for future functional experiments both in vivo and in vitro." (PMID 36213111, 2022). "Among the increased proteins following RBPMS knockdown, the two ARRB members—ARRB1 and ARRB2—are deregulated in many cancer types and have been linked to the inhibition of the senescence and growth as well as the promotion of the self-renewal, progression, and invasion of cancerous cells." (PMID 35008958, 2022). "Together, these results suggest that ARRB1 may be an important factor influencing or predicting the response of cancer patients to immunotherapy." (PMID 36213111, 2022). "However, few studies have focused on investigating the immunotherapeutic value of ARRB1 in human pan-cancer." (PMID 36213111, 2022). "The results showed that ARRB1 protein expression was observed in 17 cancer types." (PMID 36213111, 2022). "The current work shows that ARRB1 functions as a molecular switch that promotes stem cell properties by mediating the metabolic reprogramming towards glycolysis favored by many proliferative cancer cells and (cancer) stem cells." (PMID 33920080, 2021). "Previous studies have shown that ARRB1 is required for chemotaxis, suggesting that it may regulate the spread of cancer cells." (PMID 24837709, 2014). "ARRB1-induced pseudohypoxia may facilitate adaptation of cancer cells to growth in the harsh conditions that are frequently encountered within solid tumours." (PMID 24837709, 2014). "The ARRB1 gene maps to the chromosome locus 11q13, which is often amplified in human cancers." (PMID 24837709, 2014). "Given the induction of a pseudohypoxic response that can be reversed by re-expressing SDHA and FH, we asked whether ARRB1 might have broader effects on cancer cell metabolism." (PMID 24837709, 2014). "Thus, future therapies targeting ARRB1 would benefit from a combination of treatments targeting ARRB1 with inhibitors of mitochondrial cancer cell metabolism to combat the metabolic adaptation potential of cancer cells." (PMID 33920080, 2021). "B-arrestin-1 (ARRB1), a scaffolding protein involved in the desensitization of signals arising from activated G-protein-coupled receptors, has been shown to play a role in invasion and proliferation of cancer cells, including nicotine-induced proliferation of NSCLC." (PMID 29169318, 2017). "The ARRB1 also induce hypoxia and may help in cancer cells growth and metastasis." (PMID 28559546, 2017). "We thoroughly investigated the biological significance of EDN1/ARRB1 expression with COL1A1 or FN1 by examining their expression levels and predictive value for OS or PFS and SOC cancer staging (stages 1 + 2 or 3 + 4)." (PMID 39985042, 2025). "Noteworthy, among the top-10 upregulated genes we found cancer-related genes such as FosB proto-oncogene (FOSB; logFC = 1.89), mesothelin (MSLN; logFC = 3.06), and arrestin beta 1 (ARRB1; logFC = 1.89)." (PMID 34439473, 2021). "Therefore, ARRB1 may serve as a potential target for cancer diagnosis of GBC and related therapies." (PMID 33753990, 2021).
cancer (continued). "HMOX1, ARRB1, and PDIA3 were significantly differentially expressed in LUAD-normal and LUAD-cancer." (PMID 35957802, 2022).
neurological diseases (1 paper, 2023). "Among the top 50 database-predicted targeted genes, 8 genes (HOMER1, FRAT2, GRM5, TGFBR1, KDM3A, RGS2, ARRB1, and YWHAZ) were reported to be associated with axonal/neuronal regeneration/or neurological diseases." (PMID 36959678, 2023).
ARRB1 also shares sentences with these, for which no sentence is quoted: retinal degeneration (5 papers); adenocarcinoma (3); Huntington disease (2); myocardial infarction (2); pancreatic cancer (2); allergic rhinitis (1); asthma (1); atherosclerosis (1); B-cell CLL (1); bone cancer (1); brucellosis (1); cardiac ischemia (1); Cognitive impairment (1); colon cancers (1); congenital stationary night blindness (1); congestive heart failure (1); corticotroph adenomas (1); gastric cancer (1); genetic diseases (1); glaucoma (1); Hepatic steatosis (1); immune dysfunction (1); ischemia (1); leukemia (1); lipoma (1); liver cirrhosis (1); lung (1); mood disorder (1); Niemann-Pick disease, type C2 (1); night blindness (1).
A further 10 diseases each share a sentence with ARRB1 in 1 paper.